APOBEC3H (apolipoprotein B mRNA editing enzyme catalytic subunit 3H)
Description:
DNA deaminase (cytidine deaminase) which acts as an inhibitor of retrovirus replication and retrotransposon mobility via deaminase-dependent and -independent mechanisms. The A3H-var/haplotype 2 exhibits antiviral activity against vif-deficient HIV-1. After the penetration of retroviral nucleocapsids into target cells of infection and the initiation of reverse transcription, it can induce the conversion of cytosine to uracil in the minus-sense single-strand viral DNA, leading to G-to-A hypermutations in the subsequent plus-strand viral DNA. The resultant detrimental levels of mutations in the proviral genome, along with a deamination-independent mechanism that works prior to the proviral integration, together exert efficient antiretroviral effects in infected target cells. Selectively targets single-stranded DNA and does not deaminate double-stranded DNA or single- or double-stranded RNA. Exhibits antiviral activity also against T-cell leukemia virus type 1 (HTLV-1) and may inhibit the mobility of LTR and non-LTR retrotransposons.
Synonyms: ARP-10; A3H; ARP10
Tractability: PROTAC: UniProt records ubiquitination sites on it.
Gene: Protein-coding gene on chromosome 22 (39,097,224 to 39,104,067, forward strand). Ensembl gene ENSG00000100298.
Subcellular location: Cytoplasm; Nucleus; Cytoplasm, P-body
Subcellular location (Human Protein Atlas): Nucleoplasm; Cytosol
Pathways (Reactome):
Metabolism of RNA: Formation of the Editosome; mRNA Editing: C to U Conversion
Gene Ontology:
Molecular function: cytidine deaminase activity; protein binding; RNA binding; hydrolase activity; zinc ion binding
Biological process: clearance of foreign intracellular DNA; defense response to virus; DNA cytosine deamination; host-mediated suppression of viral genome replication; negative regulation of single stranded viral RNA replication via double stranded DNA intermediate; transposable element silencing; cytidine to uridine editing; negative regulation of viral genome replication
Cellular component: cytoplasm; cytosol; nucleoplasm; nucleus; P-body
Genetic constraint (gnomAD): Loss-of-function variants: 8 observed, 22.17 expected, observed/expected ratio (o/e) 0.36, 90% interval 0.21 to 0.65. The upper end of that interval is the gene's LOEUF score, 0.65, which puts it in group 2 of 6, group 1 being the genes least tolerant of losing a copy. Missense variants: 229 observed, 238.42 expected, observed/expected ratio (o/e) 0.96, 90% interval 0.86 to 1.07. Synonymous variants: 87 observed, 95.71 expected, observed/expected ratio (o/e) 0.91, 90% interval 0.76 to 1.09.
Homologues: Orthologues: chimpanzee APOBEC3H (95% identical), macaque APOBEC3H (83% identical), rat Apobec3 (49% identical), dog APOBEC3Z3 (46% identical), mouse Apobec3 (46% identical). Paralogues in human: APOBEC3C (36% identical), APOBEC3G (35% identical), APOBEC3F (34% identical), APOBEC3A (34% identical), APOBEC3D (34% identical), APOBEC3B (33% identical), AICDA (32% identical), APOBEC2 (27% identical), APOBEC1 (23% identical).
Diseases named in the same sentence as APOBEC3H in open-access papers:
APOBEC3H is named in the same sentence as 21 diseases in open-access papers, as found by Europe PMC text mining. Sharing a sentence is not in itself a finding about the gene and the disease. The quoted sentences say what the papers report.
breast carcinoma (5 papers, 2015 to 2026). "Interestingly, the isoforms of the apolipoprotein B mRNA-editing enzyme catalytic polypeptide-like (APOBEC3A, APOBEC3B and APOBEC3H), implicated in breast cancer carcinogenesis, were also up-regulated." (PMID 25961742, 2015). "Interestingly, we observed that expression APOBEC3H was associated with increased APOBEC-mutational signature in cervical, but not observed in breast cancer." (PMID 31533728, 2019). "In addition, except the APOBEC3H gene, we found high DNA methylation levels of the remaining APOBEC members, including APOBEC1, APOBEC2, APOBEC3A, APOBEC4, and AICDA, in both HMEC and ER− breast cancer cells." (PMID 26682542, 2015). "For other APOBEC family members, they show either extremely low (median log2-transformed RPKM < 0) mRNA levels (including APOBEC3A, APOBEC3H, APOBEC1, APOBEC2, APOBEC4, and AICDA), or no obvious expression differences between ER+ and ER− breast cancers (including APOBEC3D, APOBEC3F, and APOBEC3G)." (PMID 26682542, 2015).
COVID-19 (4 papers, 2022 to 2023). A disease caused by infection with severe acute respiratory syndrome coronavirus 2. "Interestingly, miR-6741 was recently described as a potential biomarker for the severity of COVID-19, where a transient upregulation after dexamethasone treatment was associated with a poor prognosis; APOBEC3H and HNRNPA1L2, involved in antiviral defense, were identified as target genes." (PMID 38136163, 2023). "We found a high expression of APOBEC3A, APOBEC3B, APOBEC3C, APOBEC3D, APOBEC3F, APOBEC3G and APOBEC3H in the classical, intermediate monocytes and NK cells of the COVID-19 patients compared to the healthy or recovered individuals." (PMID 36532041, 2022). "Despite these limitations, we are confident that this may serve as a steppingstone to understand the role of miR-6741-5p-regulated APOBEC3H in COVID-19 biology." (PMID 36560686, 2022).
HIV-1 infection (4 papers, 2013 to 2023). The type species of lentivirus and the etiologic agent of acquired immunodeficiency syndrome (AIDS). "We demonstrate that these stable/unstable phenotypes are an intrinsic property of endogenous APOBEC3H proteins in primary CD4+ T lymphocytes and confer differential resistance to HIV-1 infection in a manner that depends on natural variation in the Vif protein of the infecting virus." (PMID 25411794, 2014).
viral infection (4 papers, 2014 to 2023). "We found that endogenous APOBEC3H haplotypes yield stable or unstable proteins and that stable APOBEC3H is induced during viral infection and restricts the replication of isolates with naturally occurring hypo-functional but not hyper-functional Vif alleles." (PMID 25411794, 2014).
lung carcinoma (3 papers, 2015 to 2020). "The SNP may contribute to the development of lung cancer by affecting the structure and function of APOBEC3H or it may also act as proxy of multiple rare variants." (PMID 26459911, 2015). "According to these results, we suggested that rs139293 was probably associated with reduced lung cancer risk by destroying the structure of APOBEC3H and regulating the expression of APOBEC3C and APOBEC3H." (PMID 26459911, 2015).
AIDS (2 papers, 2013 to 2018). A syndrome resulting from the acquired deficiency of cellular immunity caused by the human immunodeficiency virus (HIV). "The following reagents were obtained through the NIH AIDS Research and Reference Reagent Program, Division of AIDS, NIAID, NIH: anti-ApoC17, from Klaus Strebel and Anti-Human APOBEC3H Monoclonal (P1H6) (cat # 12156) from Michael Emerman and Reuben Harris." (PMID 30233553, 2018).
breast tumour (1 paper, 2016). "Here, we extend this result to the largest available breast tumour data sets, and test the hypothesis that stably expressed variants of the only other functionally dimorphic DNA deaminase family member, APOBEC3H (A3H), are responsible for APOBEC signature mutations in the absence of A3B." (PMID 27650891, 2016).
cervical cancer (1 paper, 2020). A primary or metastatic malignant neoplasm involving the cervix. "Therefore, we also integrated the APOBEC family (APOBEC1 APOBEC3A, APOBEC3B, APOBEC3C, APOBEC3D, APOBEC3F, APOBEC3G, and APOBEC3H) mRNA expression of 176 core-set cervical carcinoma samples for multiplatform integrative analyses." (PMID 32211324, 2020).
dysplasia (1 paper, 2020). A usually neoplastic transformation of the cell, associated with altered architectural tissue patterns. "The qPCR results showed that APOBEC3H was upregulated in all HNSC cell lines and dysplasia cell line DOK compared to the normal epithelial cell line HOK." (PMID 32775421, 2020).
influenza (1 paper, 2018). An acute viral infection of the respiratory tract, occurring in isolated cases, in epidemics, or in pandemics; it is caused by serologically different strains of viruses (influenzaviruses) designated A, B, and C, has a 3-day incubation period, and usually lasts for 3 to 10 days. "As anticipated, APOBEC3G was upregulated in the influenza-infected cells, and APOBEC3H expression also increased." (PMID 29654310, 2018).
pancreatic adenocarcinoma (1 paper, 2022). "However, the role of APOBEC1, APOBEC3A, APOBEC3G and APOBEC3H in pancreatic adenocarcinoma is not clear, and related studies are very scarce, which motivated us to carry out relevant bioinformatics analysis." (PMID 36339709, 2022).
cancer (16 papers, 2018 to 2025). A tumor composed of atypical neoplastic, often pleomorphic cells that invade other tissues. "APOBEC3A, APOBEC3B, and APOBEC3H are most tightly linked to carcinogenesis due to their frequent expression in cancers, nuclear localization, and ability to deaminate cytidines in genomic DNA." (PMID 36970060, 2022). "APOBEC3H is a single-stranded DNA cytosine deaminase that can induce mutations in tumour cells, resulting in immune recognition or cancer cell death." (PMID 33685397, 2021). "Remarkably, among the top genes, in addition to some important well-known genes for each of the cancer types, we also identified three genes APOBEC3H, KIRREL1, and FAM166B, that are significantly correlated with OS for CSCC and HGSOC patients, respectively." (PMID 38172536, 2024). "APOBEC3H (A3H) is a member of the APOBEC3 subfamily of DNA cytosine deaminases that are important for innate immune defense and have been implicated in cancer biogenesis." (PMID 29491387, 2018). "APOBEC3H is a member of the apolipoprotein B mRNA‐editing enzyme catalytic polypeptide 3 families of proteins, and it induces somatic mutagenesis in cancer cells that drive tumour evolution and may manifest clinically as recurrence, metastasis and/or therapy resistance." (PMID 33048468, 2020). "APOBEC3H is a member of the Apolipoprotein B mRNA Editing Catalytic Polypeptide-like (APOBEC) family, which has been previously reported to have a significant impact on the instability of cancer genome." (PMID 38685053, 2024).
tumor (11 papers, 2015 to 2026). "To support the results, we found that the APOBE3C and APOBEC3H were co-expressed in both lung tumor and adjacent normal tissues based on TCGA database (ρ = 0.27, P = 5.51 × 10−18 in tumor tissues; ρ = 0.59, P = 1.60 × 10−11 in adjacent normal tissues)." (PMID 26459911, 2015). "Further study showed that the T allele of rs139293 was associated with the altered expression of APOBEC3H and APOBEC3C and that the two genes were co-expressed in both tumor and adjacent normal tissues." (PMID 26459911, 2015). "APOBEC3H was identified to demethylate and upregulate CXCL10 and improve CD8+ T cell tumor infiltration in the tumor microenvironment." (PMID 32775421, 2020). "APOBEC3H was identified to be a potential prognostic predictor and therapeutic target for oncoimmunotherapy in HNSC, in consideration of its essential role in regulating CXCL10-mediated immune activation and CD8+ T cell infiltration into the tumor microenvironment." (PMID 32775421, 2020).
infection (7 papers, 2014 to 2023). The state of being infected such as from the introduction of a foreign agent such as serum, vaccine, antigenic substance or organism. "We also found that APOBEC3H protein levels are induced over 10-fold by infection." (PMID 25411794, 2014).
APOBEC3H also shares sentences with these, for which no sentence is quoted: colorectal tumors (1 paper); esophageal cancer (1); head and neck squamous cell carcinoma (1); liver cancer (1); metastatic melanoma (1); metastatic tumors (1); prostate carcinoma (1).